RASSF4 (Ras association domain family member 4)
Description:
Potential tumor suppressor. May act as a KRAS effector protein. May promote apoptosis and cell cycle arrest.
Synonyms: AD037; MGC44914
Tractability: PROTAC: ubiquitination databases record sites on it.
Gene: Protein-coding gene on chromosome 10 (44,959,407 to 44,995,891, forward strand). Ensembl gene ENSG00000107551.
Subcellular location (Human Protein Atlas): Nucleoli; Nucleoplasm; Cell Junctions; Cytokinetic bridge; Cytosol; Mitotic spindle
Gene Ontology:
Molecular function: protein binding
Biological process: signal transduction
Genetic constraint (gnomAD): Loss-of-function variants: 32 observed, 31.69 expected, observed/expected ratio (o/e) 1.01, 90% interval 0.76 to 1.36. The upper end of that interval is the gene's LOEUF score, 1.36, which puts it in group 5 of 6, group 1 being the genes least tolerant of losing a copy. Missense variants: 354 observed, 358.54 expected, observed/expected ratio (o/e) 0.99, 90% interval 0.9 to 1.08. Synonymous variants: 154 observed, 144.31 expected, observed/expected ratio (o/e) 1.07, 90% interval 0.94 to 1.22.
Homologues: Orthologues: chimpanzee RASSF4 (98% identical), macaque RASSF4 (97% identical), rat Rassf4 (85% identical), mouse Rassf4 (85% identical), guinea pig RASSF4 (84% identical), dog RASSF4 (83% identical), rabbit RASSF4 (62% identical), pig RASSF4 (61% identical), tropical clawed frog rassf4 (60% identical), zebrafish rassf4a (60% identical), zebrafish RASSF4 (54% identical), Drosophila melanogaster Rassf (36% identical). Paralogues in human: RASSF2 (57% identical), RASSF6 (37% identical), RASSF1 (21% identical), RASSF5 (20% identical), RASSF3 (17% identical).
Diseases named in the same sentence as RASSF4 in open-access papers:
RASSF4 is named in the same sentence as 31 diseases in open-access papers, as found by Europe PMC text mining. Sharing a sentence is not in itself a finding about the gene and the disease. The quoted sentences say what the papers report.
alveolar rhabdomyosarcoma (4 papers, 2015 to 2025). A rapidly growing malignant mesenchymal neoplasm. "In alveolar rhabdomyosarcoma cells, the PAX3::FOXO1 fusion transcript has been demonstrated to suppress Hippo signalling through Ras associated domain family 4 (RASSF4) which modulates the activity of the MST1 kinase, leading to overexpression of YAP." (PMID 40983796, 2025). "In alveolar rhabdomyosarcoma associated with Pax3-FOXO1, RASSF4 is highly expressed and leads to YAP1 activation by the suppression of the Hippo pathway." (PMID 26690221, 2015).
colorectal cancer (3 papers, 2020 to 2025). A primary or metastatic malignant neoplasm that affects the colon or rectum. "Ras association domain family 4 (RASSF4) is a tumor suppressor protein that is widely expressed in normal tissues; however, loss of expression due to DNA hypermethylation is related to nasopharyngeal carcinoma, non-small cell lung cancer, colorectal cancer, and head and neck cancers." (PMID 32878338, 2020). "It was reported that RASSF4 participates in the development of various malignant tumors, including hepatic, gastric, and colorectal cancers, through regulating key signaling pathways such as RAS–MAPK and Hippo–YAP." (PMID 41007433, 2025). "We first examined RASSF4 protein in four colorectal cancer cell lines (HCT8, LoVo, HCT116 and HCT15) and normal colon epithelial cell line HCO‐Epic." (PMID 35611809, 2022). "The Cancer Genome Atlas (TCGA) colorectal cancer cohort revealed that the expression of RASSF4 in colorectal cancer tissues was significantly lower than that in normal colon tissues." (PMID 35611809, 2022). "In addition, we checked RASSF4 protein expression in five colorectal cancer tissues and paired adjacent normal tissues by Western blot." (PMID 35611809, 2022). "To date, the expression pattern and biological significance of RASSF4 in colorectal cancers (CRC) have not been fully investigated." (PMID 35611809, 2022).
acute myeloid leukemia (2 papers, 2025). Acute myeloid leukemia (AML) is a group of neoplasms arising from precursor cells committed to the myeloid cell-line differentiation. "In OSCC, overexpression of miR-626 targets and inhibits RASSF4 translation, whereas in acute myeloid leukemia (AML), GATA-binding protein 2 (GATA2) significantly reduces RASSF4 expression levels." (PMID 41007433, 2025).
bladder cancer (2 papers, 2012 to 2025). "We studied DNA promoter methylation of five RASSF family members (RASSF1A, RASSF2A, RASSF4, RASSF5, and RASSF6) in FFPE bladder cancer tissues and normal adjacent tissues." (PMID 22530128, 2012).
gastric adenocarcinoma (2 papers, 2022 to 2025). "RASSF4 downregulation has been implicated in several human cancers such as nasopharyngeal carcinoma, gastric adenocarcinoma, multiple myeloma and lung cancer." (PMID 35611809, 2022). "In most cancers, such as non-small cell lung cancer (NSCLC) and gastric adenocarcinoma (GAC), RASSF4 acts as a tumor suppressor by inhibiting the RAS/MAPK pathway while activating the Hippo signaling cascade, ultimately inducing cell cycle arrest and apoptosis." (PMID 41007433, 2025).
gastric cancer (2 papers, 2015 to 2025). A primary or metastatic malignant neoplasm involving the stomach. "After the RASSF4 promoter, which was coupled with the lucifease gene, was stably introduced into the gastric cancer cell lines (NCI-N87 and SNU216 cells), we examined effects of ATOH1 on the activity of luciferase." (PMID 25950549, 2015). "Studies on gastric cancer (GC) indicate that in 75% of GC tissues, RASSF4 is silenced and loses its inhibitory effect on proliferation." (PMID 41007433, 2025).
lung adenocarcinoma (2 papers, 2021 to 2025). A carcinoma that arises from the lung and is characterized by the presence of malignant glandular epithelial cells. "Further investigation will determine whether RASSF4 is the direct target of SPRR1B in lung adenocarcinoma, and further studies are needed to discover the molecular mechanisms involved." (PMID 33501784, 2021).
multiple myeloma (2 papers, 2022 to 2025). "RASSF4 acts as a key tumor suppressor in multiple myeloma (MM), and its downregulation mediated by promoter methylation promotes tumor progression." (PMID 41007433, 2025). "RASSF4 is downregulated during multiple myeloma progression and correlates with a poor prognosis." (PMID 35611809, 2022). "In vitro experiments demonstrated that treating human myeloma cell lines (HMCLs), such as XG-7, AMO-1, and JJN3, with HDACi significantly upregulated RASSF4 mRNA and protein levels, with particularly pronounced effects in cells exhibiting low baseline RASSF4 expression." (PMID 41007433, 2025).
nasopharyngeal carcinoma (2 papers, 2022 to 2025). A carcinoma arising from the nasopharyngeal epithelium. "Aberrant loss and promoter methylation of RASSF4 has been found in nasopharyngeal carcinoma." (PMID 35611809, 2022). "Additionally, 12.5% of nasopharyngeal carcinoma (NPC) cell lines exhibit RASSF4 deletion, with highly methylated promoter regions, and demethylating agents can restore its mRNA expression." (PMID 41007433, 2025).
oral squamous cell carcinoma (2 papers, 2021 to 2025). "In oral squamous cell carcinoma (OSCC), the high expression of miR-626 significantly downregulates the RASSF4 expression, thereby activating the Wnt–β-catenin pathway to promote cancer cell proliferation and drive the malignant progression of OSCC through the EMT process." (PMID 41007433, 2025).
breast carcinoma (1 paper, 2014). "Additionally RASSF4 is located in a region with frequent LOHs observed in prostate cancer and it is mutated in lung and breast cancers." (PMID 24489653, 2014).
colon cancer (1 paper, 2022). "Whether the biological role of RASSF4 in colon cancer involves NF‐kB or AP‐1 and whether it plays a protective role in vivo requires further investigation." (PMID 35611809, 2022).
diabetes (1 paper, 2012). "Finally, the group comprised of Mmp15 (matrix metallopeptidase 15), Rassf4 (ras association domain family member 4), Pfpl (pore forming protein-like), and Spi16 (serine protease inhibitor 16) responded to both diabetes and diet, in all combinations." (PMID 22701643, 2012).
hepatocellular carcinoma (1 paper, 2025). A malignant tumor that arises from hepatocytes. "In metabolic fatty liver disease (MASLD), fatty liver inflammation (MASH), and hepatocellular carcinoma (HCC), transcriptomic analyses revealed significantly downregulated RASSF4 expression." (PMID 41007433, 2025).
liver cancer (1 paper, 2025). An epithelial or non-epithelial malignant neoplasm that arises from the liver. "Similarly, in liver cancer treatment, RASSF4 overexpression can reverse tumor resistance to 5-fluorouracil." (PMID 41007433, 2025).
liver fibrosis (1 paper, 2025). "Through its diverse functions, including coordinating the blockade of liver fibrosis and stem cell fate decisions, RASSF4 serves as a central molecular switch maintaining tissue dynamic equilibrium." (PMID 41007433, 2025). "RASSF4 can serve as a biomarker for indicating MASLD disease progression and assessing HCC prognosis, and its associated pathways may provide new targets for targeted therapy in liver fibrosis and HCC." (PMID 41007433, 2025).
lung carcinoma (1 paper, 2022). "In addition, RASSF4 has been reported to be downregulated in non‐small cell lung cancers." (PMID 35611809, 2022).
neuroblastoma (1 paper, 2012). Neuroblastoma (NB) is the most common solid, extracranial childhood tumor. "In the current study, we found that several of the RASSF family genes (RASSF2, RASSF4, RASSF5, RASSF6, RASSF7, and RASSF10) to various degrees were methylated in neuroblastoma cell lines and primary tumors." (PMID 22695170, 2012).
osteosarcoma (1 paper, 2025). A usually aggressive malignant bone-forming mesenchymal neoplasm, predominantly affecting adolescents and young adults. "Conversely, RASSF4 activation promotes oncogenic signaling, as observed in osteosarcoma, where it enhances β-catenin accumulation within the nucleus." (PMID 41007433, 2025). "RASSF4 inhibits osteosarcoma cell proliferation by regulating the Wnt–β-catenin signaling pathway." (PMID 41007433, 2025).
somatotroph adenomas (1 paper, 2015). "Regarding RASSF3 and RASSF4, very little data exist, but it was reported that RASSF3 is epigenetically inactivated in somatotroph adenomas and RASSF4 in human tumor cells." (PMID 25750636, 2015).
Stroke (1 paper, 2014). Sudden impairment of blood flow to a part of the brain due to occlusion or rupture of an artery to the brain. "This phenomenon was exaggerated in aged rats by an increased expression of several new “stroke genes,” including Il13a, Rassf4, Tgfbi, and Wnt5b, in the peri-lesional cortex of aged rats only." (PMID 24672479, 2014).
tumor (17 papers, 2010 to 2025). "Building upon the established regulatory mechanisms underlying RASSF4 dysregulation, this section examines potential therapeutic approaches aimed at restoring its tumor-suppressive functions." (PMID 41007433, 2025). "RASSF4 downregulation significantly associated with advanced tumour‐node‐metastasis (TNM) stage, T status, positive node status and high Ki‐67 index." (PMID 35611809, 2022). "Notably, in different pathological types, such NSCLC and OSCC, the degree of reduced RASSF4 expression is closely associated with clinical pathological features such as the tumor stage and metastatic potential." (PMID 41007433, 2025). "Additionally, in NSCLC, reduced RASSF4 levels are strongly linked to advanced tumor node metastasis (TNM) staging, lymph node metastasis, and poor prognosis." (PMID 41007433, 2025). "Thus, epigenetic loss of RASSF4 may enable tumor cells to evade RAS-induced growth suppression, thereby promoting malignant progression." (PMID 41007433, 2025). "RASSF4 can function as either a tumor suppressor or an oncogenic activator, depending on the cellular context." (PMID 41007433, 2025). "RASSF4 is recognized as a tumor suppressor due to hypermethylation of its promoter and consequent transcriptional silencing in various cancers; however, its regulatory role is context-dependent and exhibits dual functions in different tumors." (PMID 41007433, 2025). "Its dynamic changes directly determine the switching between tumor suppression and promotion functions of RASSF4 in tumors." (PMID 41007433, 2025). "This regulatory mechanism dynamically influences tumor progression and significantly modulates the tumor-suppressive function of RASSF4." (PMID 41007433, 2025). "In most cases, as in most cancer types, RASSF4 inhibits tumor proliferation through cycle arrest, but in some other cases (such as aRMS) it acts as a pro-cancer factor." (PMID 41007433, 2025). "Although this duality of function puts higher requirements on the individualization of treatment strategies, it also highlights the unique value of targeted RASSF4 in precision tumor treatment." (PMID 41007433, 2025). "Exogenous overexpression of RASSF4 significantly inhibits cell growth and induces apoptosis, indicating that it has certain tumor suppressive activity." (PMID 41007433, 2025). "Mechanistically, RASSF4 suppresses tumor growth by modulating critical signaling pathways, including the Hippo, RAS/MAPK, and PI3K/AKT cascades, thereby influencing tumor cell fate." (PMID 41007433, 2025). "By integrating the latest research advances, this review also proposes a framework for targeted tumor intervention involving RASSF4." (PMID 41007433, 2025). "In OSCC, RASSF4 as a tumor suppressor is targeted and inhibited by miR-626 and regulated by methylation." (PMID 41007433, 2025). "Although RASSF4 exhibits tumor-suppressing effects in most tumors, it also demonstrates clear tumor-promoting functions in some tumor types such as aRMS." (PMID 41007433, 2025). "The synergistic effect of RASSF4 overexpression and multiple targeted drugs can better inhibit further tumor progression." (PMID 41007433, 2025). "These regulatory mechanisms work in concert to collectively shape the pivotal role of RASSF4 in tumor development." (PMID 41007433, 2025). "Outside of their recognition as tumor suppressors there are few functional data on RASSF3 or RASSF4." (PMID 39009833, 2024). "Seven tumor antigens (ADA, FYN, HDC, NFKBIZ, RASSF4, SLC6A3, and UPP1) associated with inferior prognoses and higher-level infiltration of antigen-presenting cells in PRAD were identified, thus promising candidates for mRNA vaccine." (PMID 35547260, 2022). "Ectopic expression of RASSF4 induces 293T apoptosis in a Ras‐dependent manner and inhibits tumour cell growth." (PMID 35611809, 2022).
tumor (continued). "For example, in non-small-cell lung cancer, M2-derived EVs containing miR-155 and miR-196a-5p led to downregulation of RASSF4, a known tumor suppressor gene, and subsequently increased tumor cell migration, invasion, and EMT." (PMID 34943937, 2021). "However, in some tumor microenvironments, RASSF4 binds to MST1 via its SARAH domain to inhibit the core kinase cascade of the Hippo pathway (MST1–LATS1–YAP), blocking pro-apoptotic signals and promoting apoptosis resistance." (PMID 41007433, 2025). "However, in specific tumor types, high RASSF4 expression paradoxically promotes tumor growth by interacting with mammalian sterile 20-like kinase 1 (MST1) to inhibit the Hippo signaling pathway." (PMID 41007433, 2025). "RASSF4 deeply participates in the pathological process of malignant tumor progression by regulating intercellular communication and metabolism in the tumor microenvironment at multiple levels, making it a key molecular target related to tumorigenesis and development." (PMID 41007433, 2025). "Although RAS mutations are frequently observed in MM and drive oncogenic signaling through pathways such as MEK/ERK and PI3K/AKT, Eva et.al indicate that the tumor-suppressive function of RASSF4 remains intact irrespective of RAS mutational status." (PMID 41007433, 2025). "RASSF4 defects lead to inactivation of tumor suppression pathways." (PMID 41007433, 2025). "Notably, RASSF4 is widely expressed in normal tissues, whereas its expression is down-regulated in tumors, suggesting that RASSF4 functions as a tumor suppressor in a range of malignant tumors." (PMID 39963112, 2025). "The tumor suppressor RASSF4, which participates in diverse biological processes including cell death, signal transduction, and tumor development, has been reported to promote EV71 infection and subsequently accelerate the inhibition of AKT phosphorylation in infected cells." (PMID 38596371, 2024). "In addition, analysis of 41 cases of paired tumour/normal samples showed that RASSF4 was lower in CRC tissues compared with corresponding adjacent normal colon tissues (Wilcoxon matched‐pairs signed‐rank test, p < 0.05)." (PMID 35611809, 2022). "RASSF4 is a member of the RASSF family of tumor suppressors." (PMID 33892787, 2021). "By contrast, 4 down-regulated genes are tumor suppressors (Lxn, Rassf4, Dusp16, Ifitm2)." (PMID 25229630, 2014). "Additionally, RASSF4 profoundly influences the tumor microenvironment and immune regulation." (PMID 41007433, 2025). "The subsequent upregulation of RASSF4 may thereby drive tumor growth." (PMID 41007433, 2025). "However, restoring the RASSF4 function can induce G2/M phase cell cycle arrest (inhibiting DNA synthesis and mitosis), thereby inhibiting cancer cell proliferation and suppressing tumor growth." (PMID 41007433, 2025). "Conversely, in aRMS, RASSF4 is upregulated by the PAX3-FOXO1 fusion oncoprotein and promotes tumor growth through MST1 inhibition and subsequent YAP activation." (PMID 41007433, 2025). "Conversely, cluster 4 was mainly characterised by the presence of genes involved in signal transduction and cell structure, including a number of tumour suppressor genes (FAT-2, DCC, RASSF-4 and BRAF) that play a role in the control of cell proliferation." (PMID 20700504, 2010). "Combination with MEK inhibitors enhances the inhibitory effect on KRAS-mutant tumors, while co-administration with YAP inhibitors synergistically inhibits tumor metastasis; in tumors with abnormal activation of the PI3K/AKT pathway, RASSF4 overexpression enhances the efficacy of PI3K inhibitors." (PMID 41007433, 2025). "Studies also suggest that RASSF4 inhibits mitogen-activated protein kinase (MAP kinase) signaling by suppressing the phosphorylation of extracellular signal-regulated kinase (ERK), providing another potential mechanism for RASSF4-mediated tumor suppression." (PMID 41007433, 2025).